ACBD6 (acyl-CoA binding domain containing 6)
Description:
Binds long-chain acyl-coenzyme A molecules with a strong preference for unsaturated C18:1-CoA, lower affinity for unsaturated C20:4-CoA, and very weak affinity for saturated C16:0-CoA. Does not bind fatty acids. Plays a role in protein N-myristoylation.
Synonyms: MGC2404; LHX4-AS1; NEDPM
Tractability: PROTAC: ubiquitination databases record sites on it; its protein half-life has been measured.
Gene: Protein-coding gene on chromosome 1 (180,269,653 to 180,502,954, reverse strand). Ensembl gene ENSG00000230124.
Subcellular location: Cytoplasm; Nucleus
Subcellular location (Human Protein Atlas): Nucleoplasm; Cytosol
Pathways (Reactome):
Metabolism: Mitochondrial Fatty Acid Beta-Oxidation
Gene Ontology:
Molecular function: enzyme activator activity; fatty-acyl-CoA binding; lipid binding; protein binding
Biological process: protein myristoylation
Cellular component: cytoplasm; cytosol; nucleus
Genetic constraint (gnomAD): Loss-of-function variants: 20 observed, 28.04 expected, observed/expected ratio (o/e) 0.71, 90% interval 0.5 to 1.04. The upper end of that interval is the gene's LOEUF score, 1.04, which puts it in group 4 of 6, group 1 being the genes least tolerant of losing a copy. Missense variants: 308 observed, 315.64 expected, observed/expected ratio (o/e) 0.98, 90% interval 0.89 to 1.07. Synonymous variants: 103 observed, 124.42 expected, observed/expected ratio (o/e) 0.83, 90% interval 0.7 to 0.98.
Homologues: Orthologues: chimpanzee ACBD6 (100% identical), macaque ACBD6 (99% identical), dog ACBD6 (89% identical), rat Acbd6 (87% identical), guinea pig ACBD6 (87% identical), mouse Acbd6 (86% identical), rabbit ACBD6 (76% identical), pig ACBD6 (73% identical), zebrafish acbd6 (62% identical), tropical clawed frog acbd6 (58% identical), Drosophila melanogaster anox (29% identical), Caenorhabditis elegans acbp-5 (25% identical).
Diseases named in the same sentence as ACBD6 in open-access papers:
ACBD6 is named in the same sentence as 22 diseases in open-access papers, as found by Europe PMC text mining. Sharing a sentence is not in itself a finding about the gene and the disease. The quoted sentences say what the papers report.
mental retardation (2 papers, 2020 to 2024). "Homozygous mutations in the ACBD6 gene have been associated with neurodevelopmental disorders such as mental retardation, autosomal recessive microcephaly, etc., leading to intellectual disability as the lack of myristoylation deficiency affects brain functions." (PMID 39507054, 2024).
Alzheimer disease (1 paper, 2024). A progressive, neurodegenerative disease characterized by loss of function and death of nerve cells in several areas of the brain leading to loss of cognitive function such as memory and language. "This research has identified several genes potentially involved in lipid metabolism in Alzheimer’s disease, including CHAT, RAB4A, ACBD6, and GLA." (PMID 39507054, 2024).
Ataxia (1 paper, 2024). Ataxia refers to impaired coordination of voluntary muscle movement. "In summary, we have shown that bi-allelic pathogenic variants in ACBD6 are associated with a new and distinct neurodevelopmental disease with a complex and progressive dystonia-parkinsonism-ataxia phenotype." (PMID 37951597, 2024).
Cognitive impairment (1 paper, 2024). Abnormal cognition is characterized by deficits in thinking, reasoning, or remembering. "The significance of ACBD6 is highlighted by the association of its genetic mutations with the development of neurodegenerative disorders, including cognitive impairment, in humans." (PMID 39507054, 2024).
Dystonia (1 paper, 2025). An abnormally increased muscular tone that causes fixed abnormal postures. "Screening our data for proposed dystonia candidate genes identified presumably pathogenic variants in CHD6, KCNN2, KLC1, NR4A2, and ZMYND11, but not in others, for example, ATP5F1B, ACBD6, CIZ1, SHQ1, and SPTBN1." (PMID 40533913, 2025). "No carriers of presumably pathogenic variants in other dystonia candidate genes were detected among our 1924 patients, including the recently proposed genes ATP5F1B, ACBD6, and SPTBN1." (PMID 40533913, 2025).
prostate carcinoma (1 paper, 2015). A carcinoma that arises from epithelial cells of the prostate gland. "Two newly-associated genes with potential relationships to NFκB and prostate cancer were also recovered: Menin (MEN1) and acyl-CoA binding domain containing 6 (ACBD6)." (PMID 26157642, 2015). "Our prediction suggests a more specific role for ACBD6 in prostate cancer as a potential suppressor of NFκB activity and downstream inflammation, as it was highly co-expressed with the two NFκB inhibitors, NFκB IA and NFκBIE." (PMID 26157642, 2015).
neurodevelopmental disorder (3 papers, 2020 to 2024). A behavioral and cognitive disorder with onset during the developmental period that involves impaired or aberrant development of intellectual, motor, or social functions. "Skin-derived fibroblasts of two unrelated individuals with neurodevelopmental disorder and carrying loss of function mutations in the ACBD6 gene were deficient in protein N-myristoylation." (PMID 32108178, 2020). "Mutations disrupting the coding sequence of the ACBD6 gene were identified in two unrelated individuals with neurodevelopmental disorder." (PMID 32108178, 2020).
autosomal recessive disease (1 paper, 2023). Autosomal recessive form of disease. "With our study, we provided Moderate or Strong level of evidence for GDR for 11 genes that were not listed in OMIM as having phenotype entity: FBRSL1, AGR2, ACBD6, C1orf127, PAN2, VPS50, KCTD3, NOTCH3 (for autosomal recessive disease), FAT1, NRAP, and SCLT1." (PMID 39669245, 2023).
movement disorder (1 paper, 2024). Neurological conditions resulting in abnormal voluntary or involuntary movement, which may impact the speed, fluency, quality and ease of movement. "The present study provides evidence that bi-allelic pathogenic variants in ACBD6 lead to a distinct neurodevelopmental syndrome accompanied by complex and progressive cognitive and movement disorders." (PMID 37951597, 2024). "Here, we describe 45 affected individuals from 28 unrelated families with 18 bi-allelic predicted loss-of-function (LOF), 1 missense and 1 in-frame insertion variants in ACBD6 presenting a new and distinct neurodevelopmental syndrome with a complex and progressive movement disorder phenotype." (PMID 37951597, 2024).
neurodegenerative disease (1 paper, 2024). A disorder of the central nervous system characterized by gradual and progressive loss of neural tissue and neurologic function. "Although current knowledge of the phenotype associated with ACBD5 defects is limited to only four reported families, similar to ACBD6, individuals with defective ACBD5 seem to exhibit a neurodegenerative disease, albeit with a different range of associated symptoms." (PMID 37951597, 2024).
tumor (1 paper, 2024). "Our research leveraging both scRNA-seq and bulk-seq data revealed significant differences in ACBD6 expression between normal and tumor tissues in MM, with high ACBD6 expression correlating with notably lower OS (p < 0.001)." (PMID 38916672, 2024).
ACBD6 also shares sentences with these, for which no sentence is quoted: infection (2 papers); autism spectrum disorder (1); cancer (1); developmental delay (1); epilepsy (1); frontotemporal dementia (1); lung carcinoma (1); microcephaly (1); neurological diseases (1); Parkinsonism (1); undifferentiated sarcoma (1).